PRMT2 (protein arginine methyltransferase 2)
Diseases named in the same sentence as PRMT2 in open-access papers (continued):
Sharing a sentence is not in itself a finding about the gene and the disease.
diabetes (3 papers, 2015 to 2022). "Genetic deletion of PRMT2 has been associated with a lean, leptin-hypersensitive “anti-diabetes-like” phenotype in mice." (PMID 36585686, 2022). "Thus, the loss of PRMT2 expression by genetic deletion under normoglycemic conditions or upon reduced expression in diabetes promotes apoptosis resulting in a larger necrotic area." (PMID 35835907, 2022). "We identified protein arginine methyltransferase 2 (PRMT2) as a protein whose expression in macrophages is reduced in hyperglycemia and diabetes." (PMID 35835907, 2022). "The ability of PRMT2 deficiency to phenocopy the effects of diabetes in the regression, but not progression, setting implies that it would be more of an important factor in people undergoing risk factor reduction than during the unabated progression of their disease." (PMID 35835907, 2022). "As with the plaque macrophage content data and retention data, diabetes did not exacerbate the effects of PRMT2-deficiency, again implying that another major effect of hyperglycemia is mediated through its downregulation of PRMT2." (PMID 35835907, 2022).
gastric cancer (3 papers, 2021 to 2025). A primary or metastatic malignant neoplasm involving the stomach. "Both CD44 and PRMT2 were up-regulated in gastric cancer tissues, and associated with unfavorable survival of patients." (PMID 39815331, 2025). "Very recently, a decrease in PRMT2 expression in cardia gastric cancer tumors has been observed, which suggests a potential antitumor activity played by PRMT2." (PMID 34833139, 2021). "Based on over-lapping analysis of top 60 changes in alternative splicing events (|ΔPSI|≥ 50%, P < 0.05) in MKN-45 cells over-expressing SNORA37 and gastric cancer tissues, only CD44 and PRMT2 were found to exhibit consistent alternative splicing events and selected for further analysis." (PMID 39815331, 2025). "Previously not investigated status of ASL, PRMT2, and ORNT1 warrants further functional studies on the role and clinical significance of enzyme downregulation in gastric cancer." (PMID 34439753, 2021).
renal cell carcinoma (3 papers, 2023 to 2025). "In addition, we assessed PRMT2 expression in different renal cell carcinoma cell lines using western blotting." (PMID 37173306, 2023). "In renal cell carcinoma (RCC), PRMT2 promotes cancer cell proliferation and migration, while also activating WNT transcription." (PMID 40869229, 2025).
acute myeloid leukemia (2 papers, 2024 to 2025). Acute myeloid leukemia (AML) is a group of neoplasms arising from precursor cells committed to the myeloid cell-line differentiation. "PRMT2 is a key regulator of inflammation in acute myeloid leukemia." (PMID 38902349, 2024). "PRMT2’s discovery in acute myeloid leukemia (AML) is of critical importance, as it reveals the role of PRMT2 beyond the cancer cells themselves." (PMID 41154773, 2025). "PRMT2 expression is increased in several cancer types although its role in acute myeloid leukemia (AML) remains unknown." (PMID 38902349, 2024).
cardia (2 papers, 2021). "Gastric tumors had upregulated NOS2 and downregulated ASL, PRMT2, ORNT1, and DDAH1 expression." (PMID 34439753, 2021).
colitis (2 papers, 2022 to 2024). Inflammation of the colon. "Higher PRMT2 expression is observed in intestinal specimens from patients with Crohn’s disease and ulcerative colitis, additionally, PRMT2 represses the SOCS3 promoter via histone H3R8 asymmetric dimethylation, thereby promoting the development of DSS-induced colitis." (PMID 38172698, 2024).
Down syndrome (2 papers, 2011 to 2024). "Ms4Yah mice monosomic for the Prmt2–Cstb region on Mmu10 were crossed with the Down syndrome mouse model Tc1, trisomic for ∼81% of the Hsa21 genes, to test the role of the 47 mouse genes with homologues in human present in the Prmt2–Cstb region in the phenotypes observed in Tc1 mice." (PMID 21047530, 2011).
Hyperglycemia (2 papers, 2015 to 2022). An increased concentration of glucose in the blood. "As noted in the Introduction, hyperglycemia was associated with decreased expression of Prmt2 in macrophages in vitro." (PMID 35835907, 2022). "Whereas the induction of Arg1 and Fizz1 by IL-4 was blunted, as expected, by hyperglycemia, the effect of PRMT2-deficiency in BMDMs is similar to that of hyperglycemia in that the levels of Arg1 and Fizz1 were lower than the corresponding values for the sufficient cells." (PMID 35835907, 2022). "The efficiency of monocyte labeling was not affected by either hyperglycemia or PRMT2 deficiency (not shown)." (PMID 35835907, 2022). "This suggests that hyperglycemia affects Prmt2 expression in vivo." (PMID 26288135, 2015).
acute promyelocytic leukemia (1 paper, 2024). An aggressive form of acute myeloid leukemia (AML), characterized by arrest of leukocyte differentiation at the promyelocyte stage, due to a specific chromosomal translocation t(15;17) in myeloid cells. "Thus, to define the extent of PRMT2 involvement in AML initiation and maintenance, we analyzed PRMT2 expression in 371 patients with de novo AML (excluding acute promyelocytic leukemias) using data from The Leucegene Project." (PMID 38902349, 2024).
brain tumor (1 paper, 2018). "Among the oncogenic signaling pathways, the JAK-STAT signaling pathway, which is critical for brain tumor development, is strikingly inhibited in PRMT2-depleted TPC1115 cells as shown by the GSEA and WB analyses." (PMID 30382083, 2018).
cognitive deficits (1 paper, 2011). "This analysis complete the analysis for the smaller interval from Col6a1 to Prmt2 studied previously as a model of Monosomy 21 and enables us to better understand the role of the telomeric region of Hsa21 and to decipher the mechanisms leading to cognitive deficits in DS." (PMID 21047530, 2011). "Thus we conclude that the genes conserved between mouse and human, found in the most telomeric part of Hsa21, and trisomic in Tc1, are not contributing to the major Tc1 phenotypes, suggesting that the Cstb–Prmt2 region is not playing a major role in locomotor and cognitive deficits found in DS." (PMID 21047530, 2011).
colorectal cancer (1 paper, 2023). A primary or metastatic malignant neoplasm that affects the colon or rectum. "In parallel with the discovery of the PRMT2/4 complex, another group identified PRMT5 and PRMT6 as functionally associating enzymes as oncogenic drivers in colorectal cancer." (PMID 37863263, 2023).
depression (1 paper, 2025). "In the LPS-induced depression model, the demethylation function of m6A-modified PRMT2 mRNA is inhibited, resulting in increased expression of PRMT2 in BV2 cells and the hippocampus, while ALKBH5, SLC7A11, and GPX4 expressions decrease, facilitating ferroptosis." (PMID 40177374, 2025).
dyslexia (1 paper, 2010). A learning disorder characterized by an impairment in processing written words. "The recent identification of S100B as a novel dyslexia candidate gene along with three other genes (i.e., PCNT, DIP2A, and PRMT2) mapping to chromosome region 21q22.3 suggests that decreases in S100B expression might contribute to certain dyslexia phenotypes." (PMID 20827421, 2010).
endometrial cancer (1 paper, 2023). Primary or metastatic malignant neoplasm involving the endometrium (mucous membrane that lines the endometrial cavity). "However, there have been no reports on the involvement of PRMT2, NEK6, NACC1, ATP2A2, and TM4SF19 in endometrial cancer." (PMID 37780629, 2023).
hyperlipidemia (1 paper, 2022). "Reversal of hyperlipidemia, however, apparently allowed PRMT2 deficiency to become penetrant, based on the changes in plaque composition." (PMID 35835907, 2022).
latent infection (1 paper, 2023). "On the contrary, exogenous expression of wild-type PRMT2, rather than a methylase-deficient variant, markedly increases the latent infection of primary CD4+ T cells by HIV-1GKO viruses." (PMID 37949879, 2023). "Flow cytometry analyses of the HIV-1GKO viral infection of activated primary CD4+ T cells from two anonymous healthy donors demonstrated that depletion of PRMT2 leads to a marked increase in the proportion of productively infected cells and a concomitant significant decrease in latent infection." (PMID 37949879, 2023).
malignant glioma (1 paper, 2018). A grade III or grade IV glioma arising from the central nervous system. "Combined with clinical data analyses and loss-of-function assays, here we confirm that PRMT2 is indispensable for the development of malignant glioma." (PMID 30382083, 2018). "Therefore, the elevated expression level of PRMT2 is an indicator of the aggressiveness of malignant gliomas." (PMID 30382083, 2018). "In the present study, we identify PRMT2 as a pro-tumorigenic factor in malignant gliomas and provide evidence that GBM cell growth and tumorigenesis is sensitive to PRMT2 depletion or inactivation in vitro and in vivo." (PMID 30382083, 2018).
prostate carcinoma (1 paper, 2023). A carcinoma that arises from epithelial cells of the prostate gland. "The results indicated that CCTα and the methyltransferase PRMT2 were increased in the prostate cancer samples compared to the adjacent normal prostate tissue considered as the control." (PMID 37958610, 2023).
pulmonary hypertension (1 paper, 2012). Increased pressure within the pulmonary circulation due to lung or heart disorder. "It is unclear whether the triplication of PRMT2 results in significant changes in ADMA concentrations in the brain, however, DS patients with pulmonary hypertension do show increased ADMA concentrations compared to non-DS patients with pulmonary hypertension." (PMID 22454637, 2012).
viral infection (1 paper, 2023). "Whether PRMT2 and PRMT6 cooperate with each other or function separately at different stages of viral infection to promote transcriptional silencing and viral latency remains to be elucidated." (PMID 37949879, 2023).
tumor (22 papers, 2014 to 2025). "Quantification of the staining revealed a strong association between the abundance of PRMT2-positive cells and higher tumor grade (p < 0.001)." (PMID 30382083, 2018). "PRMT2 can induce the polarization of tumor-associated macrophages (TAMs) towards the M2 phenotype (tumor-promoting, immunosuppressive) and inhibit the function of CD4+ and CD8+ T cells, leading to their exhaustion, thereby synergistically driving tumor progression and immune escape." (PMID 41154773, 2025). "PRMT2 is a functionally complex and highly context-dependent protein whose role oscillates between “oncogene” and “tumor suppressor”." (PMID 41154773, 2025). "These insights enhance the comprehension of how PADI4 affects tumour stemness through PRMT2 citrullination." (PMID 40078091, 2025). "For example, PRMT2/4-mediated arginine methylation is pivotal for transcription, DNA repair, and tumor growth." (PMID 40858547, 2025). "PRMT2 has been found to play a “dual role” in colorectal cancer (CRC): it intrinsically promotes tumor stemness and metastasis by activating the WNT5A/β-catenin signaling pathway and extrinsically regulates the TIME." (PMID 41154773, 2025). "The expression of PRMT1, PRMT3, PRMT4, PRMT5, and PRMT7 was elevated in tumor samples compared to normal tissue, while PRMT2, PRMT8, and PRMT9 were decreased." (PMID 40399547, 2025). "The colony formation assay demonstrated a significant decrease in tumour cell proliferation after PRMT2 knockdown." (PMID 40078091, 2025). "A meta-analysis across 21 cancer types, which had sufficient numbers of normal controls (n ≥ 3), revealed that the mRNA levels of most PRMTs, except for PRMT2/9, were significantly upregulated in tumor specimens compared with corresponding controls." (PMID 38826355, 2025). "We also used the Clinical Proteomic Tumor Analysis Consortium database (CPTAC) to determine the protein level of PRMT2 in patients with clear cell RCC." (PMID 37173306, 2023). "Our results showed that high PRMT2 expression was positively correlated with tumor size, depth of invasion, lymph node metastasis, distant metastasis, and TNM stage but not with age or sex." (PMID 37173306, 2023). "Cells depleted of PRMT2 were less able to form tumours and the mice displayed significantly prolonged survival." (PMID 33404912, 2021). "Depletion of PRMT2 expression leads to an increase in estrogen-induced CCND1 expression and promotion of cell proliferation and colony formation, indicating That PRMT2 has tumor-suppressive activity." (PMID 34006904, 2021). "Similar to PRMT2, PRMT5 activity in GBM cells has been linked to cell stemness and tumour cell ability to self-renew." (PMID 33404912, 2021). "In contrast, the PRMT2 knockdown leads to barely visible tumors in the brain sections or inhibits the tumor invasiveness." (PMID 30382083, 2018). "For both models, PRMT2 downregulation results in a significant reduction of tumor volumes as detected by the bioluminescence imaging and quantification of the luciferase activity in implanted mice brains at different time points." (PMID 30382083, 2018). "In conclusion, these results support that PRMT2 contributes to GBM tumor growth through its catalytic activity." (PMID 30382083, 2018). "Given the absence of prior reports on the role of PRMT2 in IDs family, our study is first to demonstrate that PRMT2 regulates IDs family transcription, thereby influencing its expression, which showed that PRMT2 may also regulate the tumour stemness of OSCC." (PMID 40078091, 2025). "By catalyzing H3R8me2a and methylating other non-histone substrates, PRMT2 is implicated in many cellular processes, and deregulation of PRMT2 is closely associated with tumor development." (PMID 37949879, 2023). "Prior work has shown that PRMT2 expression can have anti- or pro-tumor affects in certain systems." (PMID 38033034, 2023). "Finally, we confirmed the physical interactions of Ifi204, HIF1α, and PRMT2 in the tumor tissues using PLA." (PMID 35593921, 2022).
tumor (continued). "Furthermore, the induced expression of inactive PRMT2 (H112Q) specifically disrupted the expression of cell cycle regulated genes and reduced the in vivo tumor growth." (PMID 30382083, 2018). "Consequently, the mechanism by which PADI4‐mediated citrullination affects cisplatin resistance might involve modulating the IDs family and tumour stemness of OSCC through the de‐ubiquitination of PRMT2." (PMID 40078091, 2025). "For example, PRMT1 and PRMT2 are overexpressed in GBM and their depletion was shown to decrease tumor cell proliferation in mouse xenografts." (PMID 36425564, 2022). "Here, we report that PRMT2- and PRMT4-mediated arginine methylation is pivotal for BRD4 functions on transcription, DNA repair, and tumor growth." (PMID 36475791, 2022). "Tumor DDAH1 was upregulated in 11% of patients and downregulated in 33% (p = 0.050) and PRMT2 was upregulated in 15% of patients and downregulated in 33% (p = 0.120)." (PMID 34439753, 2021). "We noted that, although the number of samples in GEO is limited, expression of PRMT2, PRMT4-6 and PRMT9 is elevated in tumor samples." (PMID 34360791, 2021). "Tumor expression of NOS2 was insignificantly (ρ = −0.35, p = 0.072) and these of PRMT2 (ρ = −0.41, p = 0.036) and ASL (ρ = −0.41, p = 0.029) were significantly inversely correlated with depth of tumor invasion (T1/2–T3–T4)." (PMID 34439753, 2021). "We found that the expression levels of PRMT1, PRMT2, PRMT4, and PRMT6 are positively correlated with the tumor grades." (PMID 30382083, 2018). "Considering the alterations in PRMT2 that influence the transcription of ID1, ID2, and ID3, we demonstrated that PRMT2 may also regulate the tumour stemness of OSCC." (PMID 40078091, 2025). "Notably, PRMT1, PRMT2, PRMT3, and PRMT7 exhibited upregulation, while PRMT5, PRMT6, and PRMT8 displayed downregulation in tumor." (PMID 37781030, 2023). "IHC staining showed that the expression of PRMT2 was strongly increased in RCC tumor tissues compared to normal tissues." (PMID 37173306, 2023). "Noteworthy, PRMT2 was recently reported to be induced and contribute to HCC tumorigenesis, DIDO1 has been involved in numerous types of tumors, and PRDM2 is a tumor suppressor epigenetically repressed in HCC." (PMID 37620598, 2023). "In this study, PRMT1, PRMT2, PRMT5, and PRMT8 were significantly highly expressed in After Tumor." (PMID 38136558, 2023). "Tumor ASL and PRMT2 expression was inversely related to local advancement." (PMID 34439753, 2021). "Overexpression of PRMT2 in GBM pathogenesis makes it a potential target for tumor therapy but a potent small molecule inhibitor of PRMT2 has not yet been designed." (PMID 33440687, 2021). "Unlike main isoforms, tumor PRMT2 expression was clearly downregulated in CA and reflected the depth of tumor invasion." (PMID 34439753, 2021). "Collectively, our study reveals a previously unrecognized regulatory mechanism elucidating that PRMT2/4-mediated arginine methylation of BRD4 directly promotes the BD1 binding to acetylated histones/chromatin and consequently regulates BRD4-mediated transcription, DNA repair, and tumor growth." (PMID 36475791, 2022).